APP (amyloid beta precursor protein)
Diseases named in the same sentence as APP in open-access papers (continued):
Sharing a sentence is not in itself a finding about the gene and the disease.
cancer (continued). "Androgen signaling modulates APP processing in cancer, particularly through the non-amyloidogenic pathway; however, significant knowledge gaps remain." (PMID 41614805, 2025). "All these findings suggest a potential molecular link between APP and HGprt in LND and cancer." (PMID 40717738, 2025). "The log fold changes and, thus, the rankings among all the DEGs are almost the same for each of the found key genes ITGA2B, FLNA, GRB2, FCGR2A, and APP across all three datasets, confirming that these are consistently differentially expressed in NSCLC vs. healthy/non-cancer." (PMID 41226816, 2025). "We found no studies investigating the role of androgens on APP processing in any other cancer types." (PMID 41614805, 2025). "Collagens, MIF, MDK, APP, and laminin were the most highly expressed, and the top ligand-receptor interactions were CAF derived THBS2/THBS3 with cancer cell CD47, and CAF-derived MDK with cancer cell NCL/SDC2/SDC4." (PMID 38525245, 2024). "Interestingly, the regulation of APP is mediated by histone deacetylase in HCC, suggesting the importance of epigenetic modifications in the development of cancer." (PMID 39123408, 2024). "APP has been found to be expressed in non-neuronal tissues and overexpressed in several types of cancer." (PMID 39109301, 2024). "Outgoing signaling patterns upregulated in LE-LE signaling, relative to TC-TC signaling, included Collagen, Laminin, Tenascin, FN1, MIF, APP, CD99, Notch, and CSPG4 pathways, reinforcing the role of these pathways in facilitating cancer invasion and metastasis." (PMID 37596273, 2023). "Many papers in the literature investigate the role of APP in regulating inflammation and angiogenesis in the brain, but very little is known about the role of secreted APP or APLP2 in these processes in the context of cancer, let alone TNBC." (PMID 36768435, 2023). "Supermeres harbor multiple cargos that are related to a large panel of pathologies, including Alzheimer’s (e.g., amyloid precursor protein, APP) and cardiovascular (e.g., angiotensin-converting enzyme, ACE) diseases as well as cancer (e.g., MET proto-oncogene and receptor tyrosine kinase)." (PMID 36291183, 2022). "Collagens, MIF, MDK, APP, and laminin were detected as the most significant signaling, and the top ligand-receptor interactions THBS2/THBS3 (CAFs)—CD47 (cancer cells), MDK (CAFs)—NCL/SDC2/SDC4 (cancer cells) as potential therapeutic targets." (PMID 36352420, 2022). "A study on lung cancer metastasis found that cancer cells activate endothelial cell necroptosis through APP and death receptor 6 (DR6) during metastasis and that necroptosis disrupts the integrity of the blood vessel wall, thus providing a pathway for cancer cells to metastasize." (PMID 36038533, 2022). "Furthermore, APP and APLP are known to participate in the progression, proliferation, and migration of cancers cells." (PMID 34066808, 2021). "According to some studies, the expressions of APP and APLP differ in many types of cancers." (PMID 34066808, 2021). "Therefore, we predicted VEGFA, APLN, and AGT genes as paracrine effectors for the cancer-stroma interaction in KIRCs, whereas DLL4, APP, and TGFB1 genes to be potential autocrine effectors." (PMID 35079698, 2021). "In addition, hsa-mir-106b-5p also targets genes that play an important role in immunity such as APP, VEGFA, KAT2B, MAPK8, and AGO1 and this miR-mRNA binding allows post-transcription disruption of these genes to influence cancer development." (PMID 33773548, 2021). "For example, the CTHRC1-FZD6 pair and the APP-TNFRSF21 pair may significantly promote tumorigenesis and the proliferation of cancer cell." (PMID 33777800, 2021). "Six were common for cancer stage (Up: GDF15, TIMP1, IL1RL1; Down: CCL22, APP, CLEC1B)." (PMID 33334063, 2020). "However, multiple published studies have used different genes (e.g., KRAS, BRAF, APP, ACTB, GAPDH, 16s rRNA, ALU, LINE 1) as biomarkers to determine cfDI in various cancers." (PMID 31620364, 2019).
cancer (continued). "Aducanumab has not yet been tested for any effect regarding platelets or cancer; however, it might be a valuable addition against one of the consistently emerging key proteins, APP, that aducanumab was shown to effectively target." (PMID 41226816, 2025). "Additionally, APP and APP-like protein-2 (APLP2) have been suggested to act as tumor growth factors in the pathogenesis of several somatic tissue cancers, and they may be used as potential biomarkers to guide clinical diagnoses and the treatment of cancers." (PMID 40717738, 2025). "Interestingly, despite the absence of cancer formation, several cancer pathways were upregulated in female APP mutant mice treated with AOM/DSS." (PMID 41279101, 2025). "Currently, no studies have investigated the effect of IGF-I on APP expression in cancer." (PMID 41614805, 2025). "However, in non-neural tissues, APP has been suggested to play a central role in growth and angiogenesis, while APP overexpression has been shown in several cancers, implying its role in tumor proliferation." (PMID 37511924, 2023). "Here, a FePSe3‐based theranostic agent, FePSe3@APP@CCM, loaded with anti‐PD‐1 peptide (APP) as the inner component and CT26 cancer cell membrane (CCM) as the outer shell is reported, which acts as a multifunctional agent for MR and PA imaging and photothermal and immunotherapy against cancer." (PMID 33511018, 2021). "APP and SUMO2, which play an important role in protein homeostasis with reported involvement in cancer, and MAPK1, a kinase that regulates cell cycle and is well-known for its roles in cancers, were among the top 10 genes exhibiting the highest frequencies in PIE-MINs of at least two cancer types." (PMID 28765560, 2017). "We still do not know whether carcinoma cells themselves process APP to generate Aβ." (PMID 34592066, 2022). "It is not known whether APP is glycosylated at Y681 in cancer and RA patients." (PMID 32435655, 2020). "By contrast, stromal upstream regulators that were not estimated to be paracrine effector genes, such as DLL4, APP, and TGFB1, showed no significant increase in expression levels in KIRC cancer components compared with CCLE or GTEx." (PMID 35079698, 2021). "Furthermore, APP and APLP have been reported to influence several cancers, although the signaling pathways responsible are not understood." (PMID 34066808, 2021). "APP and APLP are also expressed in non-neuronal tissues and are overexpressed in cancer cells." (PMID 34066808, 2021).
tumor (157 papers, 1995 to 2026). "This study focuses on the role of amyloid precursor protein (APP) in tumour‐associated macrophages (TAMs) within the ccRCC TME, exploring its potential as a prognostic biomarker." (PMID 38445803, 2024). "Treatment with APP-linked liposomes containing TMZ resulted in delayed tumor growth and increased survival rates (45–70%) in tumor-bearing immunodeficient mice, when compared with the non-targeted TMZ liposomes and free TMZ." (PMID 38542190, 2024). "Our study's focus on the tumour microenvironment (TME) of ccRCC, especially the role of APP in tumour‐associated macrophages (TAMs), offers novel insights into the disease's progression." (PMID 38445803, 2024). "With these six APP gene sets, the HRs representing associations between tumor junction burdens and OS favored patients with high APP scores (all HRs < 1) more so than patients with low APP scores (all HRs > 1)." (PMID 36776840, 2023). "APP staining is increased in tumor tissue, and is associated with bigger tumor size, extracapsular invasion, and spread to the lymph nodes." (PMID 26840089, 2016). "APLP2 is likewise overexpressed in cancer cells, and APLP2 and APP are linked to increased tumor cell proliferation, migration, and invasion." (PMID 26840089, 2016). "APP and its AD-causing mutations may play an active role in tumor progression and patient prognosis, particularly in males, who exhibit poorer survival with higher APP levels." (PMID 41279101, 2025). "Additionally, APP has been found to be highly expressed in tumor stromal cells, including cancer-associated fibroblasts (CAFs) and endothelial cells." (PMID 41561750, 2025). "The APP signling pathway is associated with tumor metastasis." (PMID 40092698, 2025). "The protumor effects of MIF and APP have been reported in several studies, and their potential association with PCs may explain the additional mechanisms of tumor progression." (PMID 37138324, 2023). "Phagocytic function was restored upon APP blockade or knockdown, accompanied by reduced tumor growth." (PMID 41031085, 2025). "The increased expression of neuronal markers in the colons of female APP mutant mice suggests an intriguing link between neural regulation and tumor resistance." (PMID 41279101, 2025). "For HER2-positive samples, the increase in the difference between the Ct values of HER2 and APP transcripts in tumor tissue essentially corresponded to the overexpression of the HER2 gene." (PMID 40076767, 2025). "It has been shown that APP is highly expressed in GBM when compared to controls in both GBM tumor biopsies as well as cultured GBM cell lines, suggesting an important role in tumor proliferation." (PMID 41003874, 2025). "In the APP pathway, tumor cells primarily acted as signal senders, with immune cells (T cells and myeloid cells) serving as primary receivers, and CAFs also playing a vital role." (PMID 40260248, 2025). "In contrast, female AppNL-G-F mice exhibited a notable resistance to tumor formation, suggesting a protective effect mediated possibly through sex dependent factors and/or different pathways of APP processing." (PMID 41279101, 2025). "Unlike the T cell subsets, the three B subpopulations highly expressed CD74 with the ligand APP overexpressed in the tumor cells, which suggests their potential immunosuppressive relation." (PMID 40057671, 2025). "Beyond its effects in GBM, APP has also been shown to play a critical role in tumor growth and dispersal in brain metastasis." (PMID 41003874, 2025). "We also confirmed that treatment with a neutralizing antibody against IL-13 led to reduced tumor size, proliferation, and metaplasia in APP mice." (PMID 40761291, 2025). "It is also possible that these observations reflect a context-dependent role for APP which promotes local inflammation early in tumor development while later facilitating immune evasion through suppression of adaptive immune responses." (PMID 41003874, 2025).
tumor (continued). "Several additional genes—including FSTL1, LRPAP1, MSX1, and APP—exhibited distinct immune interaction profiles, suggesting diverse roles in modulating tumor–immune dynamics." (PMID 40943183, 2025). "Recent data report that APP is expressed in 50% of GBM tumors, with 17% of cases showing expression in more than 50% of the tumor cells, and 89% of cases showing APP expression in tumor-adjacent neurons in more than 50% of cells." (PMID 41003874, 2025). "Based on the transcription-level CellChat data, MIF and APP tumor–immune signaling has a high probability of taking place in pRMS." (PMID 41373578, 2025). "After 1 week, APP levels in human tumor cells were reduced by >50% for both EPA-siRNAAPP/App and D-siRNAAPP/App." (PMID 38613388, 2024). "In tumor sphere formation assays, the sphere numbers declined after APP knockdown, and this was especially pronounced in the Huh7 cell line." (PMID 39332525, 2024). "In the APP/App case, unconjugated siRNAs did show meaningful silencing in the tumor cells, an outcome that diverged from the HTT/Htt results—though the silencing in normal brain cells was still generally higher than the silencing in tumor cells." (PMID 38613388, 2024). "APP accumulation in axons, which is typically detectable from 2 to 3 hours until up to 9 months after axonal damage, was mostly present in and around tumor necrosis, commonly as a zigzag pattern consistent with an ischemic/hypoxic genesis." (PMID 39220249, 2024). "Following activation of the APP/Ce6 agents through irradiation, ASCs were shown to play a role in tumor migration, tropism, and exhibit anticancer properties." (PMID 38681772, 2024). "Significantly, PCOLCE has been identified as an extracellular tumor-suppressing protein known to bind to APP, thus shedding light on its role in the observed effects." (PMID 38389836, 2024). "This study aims to delve deeper into the role of APP within the ccRCC tumour microenvironment, particularly in relation to TAMs, and to explore its potential as a prognostic biomarker." (PMID 38445803, 2024). "We believe that APP is secreted by macrophages and plays a protective role, which is lost when APP is depleted, leading to tumour progression." (PMID 38445803, 2024). "In all cases, APP was also expressed by tumor-adjacent neurons with 89% expressing it in more than 50%." (PMID 39220249, 2024). "Exploring receptor-ligand interactions, we observed that aDCs and CD8+T cells primarily collaborated in executing anti-tumor functions through APP|CD74 and COPA|CD74 receptor-ligand pairs." (PMID 38565865, 2024). "Tissue microarray analyses revealed that APP expression was elevated in peritumoral compared to tumour tissues." (PMID 38445803, 2024). "Tumor sphere assay showed rescued spherogenesis in CSCs treated with cerulenin and APP, especially a dose-dependent rescue effect in Huh7 CSCs." (PMID 39332525, 2024). "The δ-secretase cleaves APP at the N585 site, generating the 586–695 fragment of APP, and can also trigger apoptosis and tumor metastasis by hydrolyzing phosphatidylinositol on the cell membrane." (PMID 39634655, 2024). "APP expression in tumor cells and neurons was confirmed upon double labeling of APP with Nestin and APP with NeuN, and the semiquantitative ratings were confirmed by quantifications of double-labeled cells across 3 regions of interest per case." (PMID 39220249, 2024). "In the analysis of L/R pairs, the L/R pairs of MIF/(CD74 + CD44 or + CXCR4) and APP/CD74 were the most prominent interactions involving signal transduction from tumor cells to PCs." (PMID 37138324, 2023). "This revealed several strong putative interactions between GBM tumor cell ligands and macrophage receptors that were conserved over the different co‐cultures, including APP:CD74, CD99:PILRA, PTN:ALK, and CLU:TREM2." (PMID 37791581, 2023).
tumor (continued). "Even if tumor junction burden didn’t directly demonstrate a predictive role, its strong correlation with “antigen presentation and antigen processing” (APP) gene signatures predicted longer OS." (PMID 36776840, 2023). "Treatment with EGCG affected both tumor growth and apoptosis via activating the caspases 3 & 7 and decreasing amyloid precursor protein (APP) levels." (PMID 37305348, 2022). "Based on the results of CellPhoneDB, the CD74-MIF/COPA/APP interactions between B cells, dendritic cells, macrophages and epithelial cells were identified in the residual tumor compared with tumor bed." (PMID 35784460, 2022). "After irradiation of the APP/Ce6 agents (808 and 660 nm) allowing activation, the role of ASCs was demonstrated in tumor migration, tropism and anticancer properties in in vitro and in vivo models." (PMID 36209478, 2022). "Remarkably, most of the 20 prioritized ligands such as APP, EGF, and IL6, were associated with the process of tumor formation, progression, and invasion as well as confronting the anti-tumor immune response." (PMID 35812726, 2022). "We found CAFs which highly expressed CTHRC1 (from F04 and F08) and tumor associated macrophages were mediated by a different set of ligand-receptor pairs, including THY1/aXb2 complex, GRN/TNFRSF1A, CD99/PILRA, CD74/MIF, APP/CD74, ANXA1/FPR1, etc." (PMID 35928443, 2022). "We also identified two miRNA/mRNA pairs, including miRNA-660-5p and miRNA-664a-5p/APP, in isolated carcinomatous glands from the same tumor (model B)." (PMID 35875068, 2022). "MPP-2 can intercept and cleave short peptides in the APP-DOX structure, and increase the hydrophobicity of the nanoparticles, leading to the further accumulation of APP-DOX at tumour site." (PMID 34630113, 2021). "BD also demonstrated therapeutic potential by interfering with the tumor cell–TME interactions by reducing the amyloid beta precursor protein and CD44 expression." (PMID 34685653, 2021). "With the benefits from its flexible geometry and multivalent direction and its distinct NIR-II fluorescent nature, intraperitoneally injecting APP-Ag2S-RGD shows great investigation sensitivity while performing surgery on the tumor." (PMID 34790654, 2021). "Silencing-mediated knockdown of APP in tumor cells resulted in normal proliferation and cell survival and basal migratory activity." (PMID 34066808, 2021). "In particular, two different publications addressed the role of sAPP as driver of the proliferative phenotype in these two types of tumors, demonstrating that silencing of APP results in a reduced proliferation capacity of tumor cells." (PMID 33926496, 2021). "Due to the high level of MMP-2 in the tumour, the MMP-2 sensitive peptide will be degraded to release the PEG segment, which results in the accumulation of APP-DOX inside the tumour." (PMID 34630113, 2021). "After establishing the critical role of APP in EGCG‐induced tumour cells apoptosis, we further identified HuR protein as the upstream mechanisms." (PMID 30793483, 2019). "Transiently transfected with HuR plasmids in tumour cells obviously eliminated the effect of EGCG‐down‐regulated expression of APP and ADAM10." (PMID 30793483, 2019). "Increased APP protein levels were observed in GBM tumours and APP metabolites are enriched in exosomes purified from brain tissues." (PMID 27770278, 2017). "Consistent with the findings in cell culture models, APP-kd cells showed significantly reduced tumor forming ability in vivo compared to control." (PMID 25491510, 2014). "As an independent experiment, we subcutaneously injected further reduced numbers (2.5×105) of MDA-MB-231 cells (groups of control and APP-kd) and then measured tumor size over time." (PMID 25491510, 2014). "As a result of measurement up to 28-days post injection, there was a significant difference in tumor volume between control and APP-kd groups." (PMID 25491510, 2014).